MTOR (mechanistic target of rapamycin kinase)
Diseases named in the same sentence as MTOR in open-access papers (continued):
Sharing a sentence is not in itself a finding about the gene and the disease.
tumor (continued). "Importantly, NR6A1 is reported as an oncogene in HCC: it is up-regulated in HCC patients and associated with a poor prognosis; it promotes cell proliferation, migration, invasiveness, and tumor growth in vitro and in vivo, most likely through the cell cycle, mTOR, WNT, and ERBB signaling pathways." (PMID 39858538, 2025). "In the tumor microenvironment, glycolytic activation induces the expansion of bone marrow-derived myeloid precursor cells into MDSCs, which may be inhibited by the mTOR inhibitor rapamycin." (PMID 40630951, 2025). "These trends, which are comparable to previous clinical observations, suggest that distinct mutations may influence could be linked to differences in metastatic tropism through variations in downstream PI3K/AKT/mTOR signaling or tumor–microenvironment interactions." (PMID 41415546, 2025). "In addition, the downregulation of PI3K/AKT/mTOR pathway may further promote the malignant transformation of tumor cells by inhibiting the expression of cell cycle regulatory proteins." (PMID 40332288, 2025). "From a tumor biology perspective, these characteristics may stem from the ability of EGFR mutations to amplify downstream signaling cascades, particularly MEK/ERK and PI3K/AKT/mTOR pathways." (PMID 41415549, 2025). "However, there are few reports on whether Apoptin can induce the apoptosis of tumour cells by affecting the mTOR/S6K signalling pathway." (PMID 40453070, 2025). "Additionally, PI3K/AKT/mTOR signaling alters the immune landscape by promoting the recruitment of immunosuppressive cells, such as regulatory T cells (Tregs), which further dampen antitumor immunity and facilitate tumor progression." (PMID 40182139, 2025). "Therefore, targeting mTOR inhibition is believed to inhibit tumor progression." (PMID 41142018, 2025). "We propose that OCTA may serve as a more sensitive modality to assess the efficacy of mTOR inhibitors for TSC-associated RAHs, considering that blood flow is essential for tumor growth and that changes in RPC or SCP vascular density may precede the changes in maximal thickness of RAHs." (PMID 40486194, 2025). "Therefore, this review suggests that the accumulation of high levels of lactate in tumor cells may activate AMPK, which in turn reduces mTORC1 activity and indirectly weakens the PI3K/Akt/mTOR signaling pathway, thus intervening in tumor progression." (PMID 40704062, 2025). "Additionally, ID may inhibit protein synthesis by downregulating the mTOR signaling pathway, further limiting tumor cell proliferation." (PMID 41190142, 2025). "Future research should explore the combination of PI3K/AKT/mTOR inhibitors with other therapeutic modalities, such as DNA damage repair inhibitors and angiogenesis inhibitors, aiming to achieve more precise and effective radiosensitization across various tumor types." (PMID 40725100, 2025). "Additionally, pairing glycolytic inhibitors with targeted therapies targeting key signaling pathways (e.g., PI3K/Akt/mTOR) could improve treatment outcomes by disrupting both tumor metabolism and essential survival signals." (PMID 41220952, 2025). "Since multiple genes of the PI3K/Akt/mTOR signaling pathway are frequently altered in human cancers, dysregulation through mutation or amplification of genes involved in the PI3K pathway, loss of the tumor suppressor PTEN or over-activation of RTK leads to tumor progression and metastasis." (PMID 40932870, 2025). "Notably, our findings suggest that in RCC progression, the BCKDK/AKT/mTOR signaling axis‐mediated pro‐tumor mechanisms represent a molecular pathway distinct from the previously reported BCKDK‐regulated exosomal miR‐125a‐5p/VE‐cadherin axis that activates angiogenesis to facilitate tumor metastasis." (PMID 40789057, 2025).
tumor (continued). "Similarly, PI3K/AKT/mTOR activation, which promotes tumor cell survival during chemotherapy, concurrently upregulates immunosuppressive cytokines such as IL-6, thereby fostering a hostile tumor microenvironment (TIME) to T-cell activity." (PMID 40650040, 2025). "Similarly, M2-like tumor-associated macrophages in anaplastic thyroid carcinoma have been shown to promote tumor stemness and metastasis by secreting IGF-I/II and activating the IR-A/IGF-IR–mediated PI3K/AKT/mTOR pathway." (PMID 40630213, 2025). "PTEN positivity suggests no loss of this mTOR regulator in the tumor." (PMID 40584698, 2025). "The mTOR signaling pathway plays a critical role in immune regulation by integrating diverse environmental inputs in the TME, involving CD8+ and CD4+ lymphocytes, regulatory T cells (Tregs), macrophages, myeloid‐derived suppressor cells, endothelial cells, and tumor‐associated fibroblasts." (PMID 41322031, 2025). "Metformin may help prevent and reduce tumor growth by inhibiting the mTOR pathway." (PMID 40969386, 2025). "Notably, SESN2 expression was inhibited in PCa and may exert tumor-suppressive effects by affecting the AMPK/mTOR signaling pathway." (PMID 40775338, 2025). "Similarly, imagine an mTOR inhibitor (to blunt growth signaling) combined with a LAT1 inhibitor (to cut off the nutrient supply)—the tumor might find it hard to escape both." (PMID 41502503, 2025). "Regulating the mTOR signaling pathway (by inhibiting glycolysis) showed strong antitumor immune responses through promoting the development of memory CD8+ T cells that can replicate rapidly upon second exposure to tumor antigen, allowing more sufficient clearance of tumor cells." (PMID 40872545, 2025). "Therefore, we speculate that mTOR signaling may be the most important mechanism by which NR6A1 regulates tumor cell glycolysis and proliferation." (PMID 41219936, 2025). "For instance, exosome-delivered miR-199a-3p and miR-122 can specifically inhibit the mTOR and PKM2 signaling pathways, respectively, and downregulate the expression of multidrug resistance-associated proteins such as P-gp and BCRP, thereby reversing chemoresistance in tumor cells." (PMID 41301162, 2025). "Additionally, it is necessary to acknowledge that inhibiting one target may activate alternative bypass signaling pathways and potentially allow dormant tumor cells to survive (e.g., via Akt/mTOR), leading to tumor progression and drug resistance." (PMID 40669873, 2025). "Thus, mTOR/PI3K/AKT becomes a potential target for natural products that inhibit CRC tumor growth." (PMID 40342991, 2025). "Thus, this study aims to evaluate polytherapy using LASSBio-1971 and the dual PI3K/mTOR inhibitor PKI-587 to bypass tumor resistance mechanisms, accessing the synergist effect and the mechanisms of action of the polytherapy by flanking different cellular pathways involved in GB biology." (PMID 40650170, 2025). "Similarly, mutations in KRAS, particularly G12C, could alter the tumor’s response to targeted therapies like EGFR-TKIs and MEK inhibitors by activating downstream MAPK and PI3K/AKT/mTOR pathways that promote tumor survival and drug resistance." (PMID 41560751, 2025). "Intriguingly, the top 200 YAP-activated genes showed marked enrichment for three MSigDB Hallmark Pathways: TNFa signaling, mTORC1 signaling, and inflammatory response, highlighting that mTOR signaling and immune cell related processes may both be important in EY tumor initiation." (PMID 39779672, 2025).
tumor (continued). "The PI3K/Akt/mTOR pathway is known to play a critical role in cell proliferation, survival, and metabolism, suggesting that its inhibition in LrNK cells could significantly impair their anti-tumor functions." (PMID 39893278, 2025). "Therefore, mTOR has been identified as a novel target for tumor therapy." (PMID 39823500, 2025). "Moreover, the expression levels of CD86 (M1 macrophage marker) and CSF1R (M2 macrophage marker) were positively correlated with those of BECN1 (autophagy regulator) and BCL2 (only CD86) that were in turn correlated with MTOR expression in tumor B cells and in the CD86+ macrophage subtype." (PMID 41415285, 2025). "Tumor cells with PIK3CA mutations are resistant to drugs targeting epidermal growth factor receptor (EGFR) or erythroblastic leukemia viral oncogene homolog 2 (ERBB2), but may be more sensitive to mTOR and PI3K inhibitors." (PMID 41040523, 2025). "Similarly, in the same tumor model, metformin’s inhibition of mTOR signaling reduced tumorigenesis." (PMID 40248706, 2025). "However, previous research has suggested that miR-199a-3p/5p and miR-199b-3p may function as tumor suppressors in non-small cell lung cancer (NSCLC) by inhibiting the mTOR signaling pathway through targeting Rheb." (PMID 40948741, 2025). "Therefore, we further examined how RNASEH2C inhibits the mTOR pathway and whether this is key to its tumor-promoting role." (PMID 41361104, 2025). "Importantly, TIMP1 was shown to modulate the tumor immune microenvironment by inducing M2 macrophage polarization via CD63/β1-integrin-mediated activation of the AKT/mTOR signaling pathway, thereby promoting hepatic pre-metastatic niche (PMN) formation and metastatic colonization." (PMID 41511313, 2025). "Notably, the first clinical trial combining the anti-IGF-1R mAb, cixutumumab, with the mTOR inhibitor, temsirolimus, demonstrated tumor regression of more than 20% in approximately 29% of the patients and a sevenfold increase in median response duration (>14 months) in patients with ES." (PMID 41347090, 2025). "To investigate whether YAP-mediated mTOR activation contributed to tumor initiation, we treated KEY primary cells with siRNAs targeting Yap/Taz and Tead1/Tead4 as well as small molecule mTOR (INK128) and YAP-TEAD (VT104) inhibitors, and observed significant reductions in clonogenic growth." (PMID 39779672, 2025). "In addition, tumor cell-derived lactate impairs the function of natural killer T cells by inhibiting the mTOR signaling pathway and nuclear translocation of zinc finger proteins, resulting in reduced secretion of IFN-γ and IL-4 and significantly weakened anti-tumor effect." (PMID 40045411, 2025). "Additionally, TAC enhanced both the mTOR activity and the tumour growth of A498 xenografts." (PMID 38341510, 2024). "Moreover, the analysis of anti-tumor drugs suggested that the AML patients exhibiting high levels of PSMD11/14 expression may benefit from utilizing mTOR inhibitors or proteasome inhibitors." (PMID 38482057, 2024). "Furthermore, the modulation of mTOR by AMPK may be the most crucial anti-tumor effect of AMPK activation by metformin, as the inhibition of mTOR leads to downregulation of protein synthesis and cell proliferation." (PMID 38831454, 2024). "EVE combined with PI3K inhibitors (PI3Ki) exerted synergistic effects on cell and colony survival in rat GH3 and human GH-PAs cell lines, which may be attributed to the fact that PI3Ki enhanced the anti-tumor effect of EVE by modulating the PI3K/Akt/mTOR and MAPK pathways." (PMID 39736867, 2024). "Furthermore, SHH signalling interacts with pathways like Wnt/β-catenin, Notch, and PI3K/Akt/mTOR, suggesting that combination therapies targeting these interactions could synergistically suppress tumour growth." (PMID 39568072, 2024).
tumor (continued). "In some tumor models, PD‐L1 expression can be stimulated by tumor extrinsic signals such as interferon‐gamma, or tumor intrinsic signals such as activation of the mammalian target of rapamycin (mTOR), and mitogen‐activated protein kinase (MAPK) signaling pathways." (PMID 38456253, 2024). "Therefore, it is advantageous to diverge from the previously recognized targets and investigate novel targets within the peripheral branches in order to further our understanding of the biological consequences of PI3K/AKT/mTOR signaling, and benefit from this anti-tumor therapeutic strategy." (PMID 38339341, 2024). "Therefore, we speculated that anthocyanins inhibit tumor cell growth by activating AMPK and inhibiting mTOR and its downstream target genes associated with fatty acid metabolism." (PMID 38716355, 2024). "Thus, the mTOR signaling pathway is a promising target in anti‐tumor therapy." (PMID 38250695, 2024). "However, it may be important to assess the mTOR activity of tumour cells before initiating mTOR inhibitor therapy." (PMID 38341510, 2024). "Several oncogenic signaling pathways, such as Akt/mTOR, JAK/STAT3, and EGFR/MAPK, or the loss or silencing of PTEN, ALK, and EGFR, are involved in the regulation of PD-L1 transcription, potentially leading to the upregulation of PD-L1 expression in tumor cells." (PMID 38762484, 2024). "Moreover, alterations in the constituent genes of the two complexes constituting mTOR, mTORC1, and mechanistic target of rapamycin complex 2 (mTORC2), also contribute to the activation of the PI3K/AKT/mTOR signaling pathway, influencing the growth of tumor cells." (PMID 38672455, 2024). "Consequently, the activation of the PI3K/AKT/mTOR signaling pathway by CD133 may enhance cisplatin resistance in the tumor microenvironment." (PMID 39456981, 2024). "The PI3K/Akt/mTOR pathway is overexpressed in nearly 50% of HCCs, and the dysregulated activation of this pathway affects a wide range of processes, including cell proliferation, metabolism, tumour cell differentiation, lipid metabolism, autophagy, and epithelial to mesenchymal transition (EMT)." (PMID 39066215, 2024). "Therefore, the uncontrolled activation of mTOR promotes tumor growth and metastasis." (PMID 38250695, 2024). "Similarly the molecular GB subgroup and specific pathway activation of the tumor tissue might influence the effect of mTOR inhibition on cell survival under temozolomide treatment." (PMID 38182566, 2024). "However, no study has been conducted yet to investigate whether HDAC7 regulate the classic AKT/mTOR pathway, which plays an indispensable role in the progression of tumour." (PMID 39431349, 2024). "Consequently, when drugs inhibiting mTOR signaling were used in diverse combinations on various types of CSCs, mostly the mTOR inhibitor showed a significant effect on reducing stem cell markers and cellular proliferation, leading to a decrease in tumor development." (PMID 39349424, 2024). "In addition, inhibition of AR‐independent signalling pathways (like Akt/mTOR pathway) by nodularin‐R may enhance the combined anti‐tumour effects." (PMID 39550701, 2024). "However, the genes predominantly expressed by the tumor types in the KO bladder are involved in tumor suppressor activities such as Gphn, which reduced mTOR pathway activation, and Ahnak, which can inhibit tumor cell proliferation and invasion as demonstrated by in vitro studies." (PMID 39769061, 2024). "Furthermore, we observed a clonal expansion and enrichment of a CD4+ Th1 population exclusively in tumours treated with combination therapy of PI3K/mTOR inhibitors and PD‐1 blockade, implying this T‐cell population is essential in supporting and maintaining CD8+ T‐cell effector function." (PMID 38711203, 2024).
tumor (continued). "The results revealed that the AMPK activator could counteract the enhanced migratory and invasive properties induced by XTP8 overexpression.To validate whether XTP8 affects tumor EMT through the AKT/AMPK/MTOR signaling pathway, we also examined the expression of EMT-related proteins." (PMID 38717641, 2024). "An STK11 mutation reduces thecapacity of tumor cells to spark off AMP kinase, resulting in a higher power strain.Moreover, STK11 has an unfavorable impact on the mTOR cascade, which may result in aberrant mTOR signaling." (PMID 40230896, 2024). "Notably, mTOR activity is activated by mutations in a variety of oncogenes and tumor suppressors, suggesting the possibility that TSC2 might be a commonly mutated tumor suppressor." (PMID 38117060, 2024). "Moreover, the PI3K/AKT/mTOR pathway also has a critical position in tumor drug resistance." (PMID 38345573, 2024). "Although not being a tumor, progressive overgrowth of the affected limb may cause cosmetic and functional problems, for which the efficacy of mTOR inhibitors has not been reported previously." (PMID 38455392, 2024). "In addition, mutations in the mTOR gene itself, which is a downstream target of PI3K/AKT, sustain the mTOR signaling pathway in a hyper-activated state, and regulate the growth and metabolism of tumor cells." (PMID 38672455, 2024). "This pathway, along with the mTOR axis, is usually coactivated in BRAF mutations, which induces the vascular endothelial growth factor receptors (VEGFR) and platelet-derived growth factor receptors (PDGFR); these receptors are crucial in sustaining the tumor growth." (PMID 39684934, 2024). "Besides, PQR309 could cross the blood-brain barrier, thus might show better anti-tumor proliferation effect than other dual PI3K/mTOR inhibitors." (PMID 38555280, 2024). "This pathway is a key regulator of mTOR-driven immune responses, such as the activation and differentiation of T and B cells as well as the antigen presenting cells and moreover, mTOR signaling has a crucial role in the development of immune evasion in the tumor microenvironment." (PMID 38600305, 2024). "In addition, the phosphatidylinositol-3-kinase (PI3K)/protein kinase B (Akt)/mammalian target of Rapamycin (mTOR) (PI3K/Akt/mTOR) pathway mediated by Ang1/Ang2-Tie2 is the main channel involved in TEMs-related tumor micro angiogenesis and immunosuppressive microenvironment." (PMID 37304233, 2023). "Consequently, assessing the mTOR pathway expression within the mass may better reflect the proliferation rate of the tumour and, consequently, its tendency to recur." (PMID 37366904, 2023). "Therefore, based on the regulatory effect of TRPML1 on mTOR, the development of regulatory drugs targeting TRPML1 activity to achieve tumor suppression may provide greater specificity and better therapeutic effects than mTOR inhibitors." (PMID 38156109, 2023). "Besides inhibitors targeting either PI3K or mTOR for tumor therapy, a number of dual PI3K/mTOR inhibitors developed to counteract treatment-induced resistance are currently being tested in phase 1 and 2 clinical trials, comprising apitolisib, bimiralisib, gedatolisib, paxalisib, and samotolisib." (PMID 37509121, 2023). "Furthermore, the underlying biological pathway in C7 was more activated in androgen response, epithelial–mesenchymal transition, fatty acid metabolism, and PI3K/AKT/MTOR signaling than those in the other cell clusters, indicating that C7 was a tumor-promoting cluster evoking by enzalutamide." (PMID 37008945, 2023). "Furthermore, nuclear mTOR was also found to be a predictor of a high-grade tumor." (PMID 37176048, 2023). "Overactivation of PIK3CA and loss of activity of PTEN due to the double mutations can lead to hyperactivation of PI3K/Akt/mTOR signaling which may result in oncogene induced senescence (OIS), potentially explaining the blockage of tumor growth in the double mutant X-3093 xenograft." (PMID 36808143, 2023).